BRAF (B-Raf proto-oncogene, serine/threonine kinase)
Diseases named in the same sentence as BRAF in open-access papers (continued):
Sharing a sentence is not in itself a finding about the gene and the disease.
colon carcinoma (continued). "Many tumors contain only a KRAS or BRAF mutation, which is consistent with previous reports finding these mutations in earlier stages of colon cancer." (PMID 20233444, 2010). "This differential impact of MEK1 and MEK2 on cell proliferation was observed in three different colon carcinoma cell lines (bearing activating mutations in either KRAS or BRAF), as well as in the breast adenocarcinoma cell line MDA-MB-231." (PMID 19014680, 2008). "Another event occurring in adenoma polyp is mutation in oncogenes, specifically in K-ras and BRAF genes in the case of colon cancer." (PMID 18718023, 2008). "The CpG island methylator phenotype (CIMP) is a distinct phenotype associated with microsatellite instability (MSI) and BRAF mutation in colon cancer." (PMID 19002263, 2008). "In one NHL, we also found D593G BRAF mutation that has also been detected in colon tumours previously." (PMID 14612909, 2003). "Proximal (right‐sided) colon cancers exhibit distinctive clinicopathological and molecular features, including larger tumour size, higher grade and mucinous histology, as well as frequent BRAF mutations and a high microsatellite instability phenotype." (PMID 40444502, 2025). "This may be due to the current cohort’s higher proportion of colon cancer patients and those with peritoneal dissemination, where the frequency of BRAF non-V600E mutations is generally low." (PMID 39941768, 2025). "BRAF mutations occur in 10% of colon cancers and are linked to poor outcomes in metastatic disease." (PMID 41294686, 2025). "Even the efficacies of molecular-targeted therapies, however, may differ among tumor types, such as reduced efficacy of BRAF- or KRAS-targeted therapy in colon cancer, possibly because of differences in the biology underlying the respective tumor development." (PMID 40726246, 2025). "BRAF mutations most commonly occur in right-sided colon cancers." (PMID 39464719, 2024). "However, in patients with gallstone-associated colon cancer, any association with consensus molecular subtypes (BRAF mutated) should be explored to identify if specific pathways are involved." (PMID 37620872, 2023). "In addition to mediating the effects of chemotherapy, protein machinery involved in DNA replication plays an important role as downstream effectors of cytotoxic effects of radiation in BRAF-mutated colon cancer cells." (PMID 37106808, 2023). "One of the most relevant upregulated secretome features associated with vemurafenib resistance in BRAF-mutated RKO colon cancer cells identified in this study included DNA replication and repair, where all highly scored hub proteins from the upregulated PPI network play an essential role." (PMID 37106808, 2023). "Recently, BRAF V600E was revealed to be a quite common mutation in colon cancer." (PMID 36647167, 2023). "Similarly, downregulation of the HSPA5/GRP78 protein expression reduced the viability of BRAF mutant colon cancer cells, which indicates that BRAF-mutated colon cancer cells are dependent on the UPR for survival." (PMID 37106808, 2023). "Moreover, recurrences of resected stage III colon cancer had significantly worse survival in BRAF mutated tumors." (PMID 36980565, 2023). "Although lower mRNA expression levels of several UPR-related proteins identified in this study were found in association with poorer median overall survival of BRAF-mutated colon cancer patients, it was only for HSPA5/GRP78 that this correlation was statistically significant." (PMID 37106808, 2023).
colon carcinoma (continued). "Given that MEK is a major downstream mediator of oncogenic BRAF in the MAPK signaling pathway, we cannot exclude the possibility that the same mechanism is involved in the development of resistance to BRAF inhibitor vemurafenib in RKO colon cancer cells harboring BRAFV600E mutation." (PMID 37106808, 2023). "The data from The Cancer Genome Atlas (TCGA) datasets, including 59 BRAF-mutated and 337 BRAF wild-type colon cancer patients, showed that the proportion of CD8+ T cells was significantly higher in BRAF-mutated colon cancer tissues than that in BRAF wild-type colon cancer tissues (P < 0.01)." (PMID 37302081, 2023). "Indeed, previous findings have demonstrated that oncogenic BRAF induces chronic ER stress in BRAF-mutated colon cancer cells." (PMID 37106808, 2023). "However, our experiment further proved that endogenous BRAF V600E is located in the mitochondria of both papillary and anaplastic thyroid cancer cells and colon cancer cells with the BRAF V600E mutation." (PMID 35748101, 2022). "Since KRAS and BRAF gene mutations are frequently present in colon cancers, we asked whether KRAS and BRAF mutations were more prevalent in GALNT6-negative tumors." (PMID 35692787, 2022). "In BRAF V600E mutated colon cancer, the use of targeted single agents has shown limited benefit." (PMID 36686797, 2022). "BRAF mutations were more frequent in right-sided colon cancers than the left-sided ones." (PMID 35592200, 2022). "We provided evidence that colon cancer patients harboring the BRAF(V600E) oncogenic mutation were lack a significant response to PLX4720, but BRAF and EGFR inhibition can be synergistic when combined, suggesting more combining targeted agents can be used in clinical trials." (PMID 35652270, 2022). "In colon cancer patients, the majority of BRAF mutations involve BRAFV600E mutation." (PMID 35592200, 2022). "Also, it is found that proangiogenic chemokines are highly expressed in BRAF mutated cell lines of colon cancer." (PMID 34381786, 2021). "Besides, survival analyses showed APC mutation had adverse impact on immunotherapy while patients with BRAF mutation were more suitable for immunotherapy in colon cancer." (PMID 34211853, 2021). "The same pattern of RanBP1 expression recorded in resistant cell lines after the treatment with vemurafenib lends further support to the idea that the development of resistance to vemurafenib in BRAF-mutated colon cancer cells is associated with centrosome amplification and mitotic progression." (PMID 34201061, 2021). "In the present study, we analyzed the differences of immune microenvironments between BRAF mutated and BRAF wild-type colon cancer utilizing datasets from The Cancer Genome Atlas and Gene Expression Omnibus and confirmed the findings by tissue specimens of patients." (PMID 34381786, 2021). "Thus, for patients with BRAF- or KRAS-mutated colon cancer, alternative targeted treatment strategies still need to be developed." (PMID 34885128, 2021). "This case series included nine patients (4 had primary tumors on the right side: 2 in ascending colon and 2 in transverse colon; and 5 on the left side: 3 in descending colon cancer and 2 in sigmoid colon) with BRAF V600E-mutated mCRC who underwent triplet therapy." (PMID 34946284, 2021). "The increased regulation of RanBP1 expression in resistant cell lines in response to PLX4032 challenge further supports the relevance of the mechanisms regulating initiation of centrosome duplication in the development of drug resistance in BRAF-mutated colon cancer cells." (PMID 34201061, 2021).
colon carcinoma (continued). "However, despite the importance of the immune microenvironment in the development and treatment of BRAF mutated colon cancer, few studies have yet investigated the pattern of tumor microenvironment in BRAF mutated colon tumors." (PMID 34381786, 2021). "In particular, the PI3K/mTOR pathway was shown to be one of the mechanisms underlying the resistance of BRAFV600E colon cancer cells to BRAF inhibition that could be overcome by concurrent BRAF and PI3K/mTOR blockade." (PMID 34201061, 2021). "Recent studies demonstrated that immune microenvironment in BRAF mutated colon tumors might lead to resistance to conventional therapies through regulation of composition of immune cell infiltration and chemokines." (PMID 34381786, 2021). "For selection of the optimal treatment of colon cancer patients with BRAF mutations, the MSI status might be considered as an additional biomarker." (PMID 34885128, 2021). "In conclusion, we found that NPM1 expression and activity potentially associated with the regulation of centrosome duplication and mitotic progression are specifically increased in BRAFV600E mutant colon cancer cells and tumor tissues from BRAF-mutated colon adenocarcinoma patients." (PMID 34201061, 2021). "Collectively, findings from this study provide ample indication that the NPM1/c-Myc axis could represent a promising therapeutic target to thwart resistance to vemurafenib in BRAF-mutated colon cancer." (PMID 34201061, 2021). "BRAF mutation is one of the most important mutation subtypes in colon cancer." (PMID 34381786, 2021). "Similarly, we found increased baseline levels of activated forms of sphingosine kinases 1 and 2 in BRAF mutated colon cancer cells resistant to vemurafenib in comparison with parental cells." (PMID 34639107, 2021). "It has been shown that BRAF mutation is observed more frequently in right-sided colon cancer than in left-sided colon cancer, which might partly explain the higher response rate to cetuximab in patients with left-sided colon cancer observed in other studies." (PMID 33347495, 2020). "This suggests that colon tumors with the particular genetic profile of RKO (BRAF mutated) may benefit most from the potential applications of VPE in anti-colon cancer strategies than KRAS mutated HCT116-like tumors." (PMID 32806531, 2020). "The present study provides more insightful knowledge of clinicopathological characteristics of TCC patients, emphasize the role of BRAF mutation since the early stage of disease and lay the basis for new treatment algorithms in this specific setting of colon cancer." (PMID 32872561, 2020). "The right side colon cancer was found to have more BRAF mutation than left side colon cancer, which might cause the resistant to anti-EGFR therapy and worsen the prognosis." (PMID 32547859, 2020). "Although response rates cannot be determined and publication bias is likely present, responses to BRAF(/MEK) inhibition clearly occur, e.g., in contrast to BRAF-mutated colon cancer, and should be considered for patients with BRAF-mutated metastatic conjunctival melanoma." (PMID 32718045, 2020). "This systematic review and meta‐analysis of mutation prevalence by tumor location among mCRC patients identified a significant difference in prevalence of both KRAS and BRAF mutations by tumor location, with mutations more frequent among right‐sided colon cancers than left‐sided tumors." (PMID 31856410, 2020). "According to the literature, the discovery of v-raf murine sarcoma viral oncogene homolog B1 (BRAF) V600E mutations indicates the possibility of colon cancer with aggressive phenotypes, and such mutations have become a significant prognostic biomarker, especially in end-stage cases." (PMID 33145020, 2020). "Since the three sub-clusters had different frequency of BRAF mutation, we speculated that BRAF inhibitors may have different sensitivity in the three sub-clusters of colon cancer cells." (PMID 31596728, 2019).
colon carcinoma (continued). "Notably, a FAK to β-catenin signaling linkage functions as an adaptive chemotherapy resistance pathway in BRAF mutated colon cancer." (PMID 31478830, 2019). "In particular, approximately 80%–90% of all BRAF mutations observed in colon cancer patients are represented by the missense mutation 1799T>A within the kinase domain of BRAF (BRAF c.1799T>A), which leads to the substitution of a valine to a glutamic acid at the position 600 (BRAFV600E)." (PMID 31083627, 2019). "The BRAFV600E mutation, which renders BRAF constitutively active with a 500-fold increase in kinase activity compared to wild-type BRAF, represents approximately 90% of all BRAF mutations observed in colon cancer patients." (PMID 31083627, 2019). "Moreover, a strong association between mutations in APC and other genes such as KRAS or BRAF and colon cancer initiation has in fact been established." (PMID 31142796, 2019). "As Vemurafenib treatment induces EGFR feedback activation, this may explain the refractoriness of BRAF (V600E) mutated colon cancers to this therapy." (PMID 29593231, 2018). "BRAF exon 15 codon 600 600Glu mutation was detected in 3 out of 86 (3.5%) colon cancer samples." (PMID 30416987, 2018). "One analysis of three independent cohorts that grouped rectal tumors with left-sided colon tumors showed that, although BRAF mutations were more prevalent in right-sided tumors, right-sided location was a negative prognostic variable independent of BRAF mutational status." (PMID 29156800, 2017). "Therefore, the aim of this study was to investigate the association of low-dose aspirin use after colon cancer diagnosis and survival of patients according to BRAF and KRAS mutation status." (PMID 28125730, 2017). "Of 63 patients with BRAF V600E-mutated mCRC and sufficient clinical data, 27 (42.9%) had right-sided colon tumors, 19 (30.2%) had left-sided colon tumors, and 17 (26.9%) had rectal tumors; 26 (41.3%) had peritoneal metastases, and 50 (79.4%) had distant lymph node metastases." (PMID 29037218, 2017). "Four patients who had right-sided colon tumors with rare BRAF mutations were identified." (PMID 29037218, 2017). "This study investigated whether the survival benefit observed in patients with colon cancer using aspirin could be associated with BRAF or KRAS mutational status." (PMID 28125730, 2017). "The majority of BRAF mutations seen in right and left colon tumors were V600E mutations (42 out of 45 [93%], right; 17 out of 22 [77%], left), which was not the case for the rectum, where only half (5 out of 10 or 50%) were BRAF V600E mutations." (PMID 29156800, 2017). "Whether CDC37 has comparable effects on other kinases in mutant BRAF colon cancer cells and whether it has similar effects on other types of cells carrying mutations in BRAF needs further investigation." (PMID 27391062, 2016). "Although how CDC37 acts differently on Akt in mutant and wild-type BRAF colon cancer cells remains unknown, it is unlikely caused by mutations in its gene as all the colon cancer cell lines included in this study harbored wild-type CDC37." (PMID 27391062, 2016). "Commonly used colon cancer cell lines frequently contain mutations in KRAS/BRAF." (PMID 27351224, 2016). "Similarly, it also remains to be determined how HSP90 interacts with Akt in mutant BRAF colon cancer cells deficient in CDC37." (PMID 27391062, 2016). "The effect of CDC37 on Akt phosphorylation, similar to its stabilizing effect on Akt, appears to be specific to colon cancer cells with activating mutations in BRAF, suggesting that mutant BRAF has reprogrammed the signaling network of protein kinases in colon cancer cells." (PMID 27391062, 2016). "Importantly, compared with KRAS-mutated TSA, BRAF-mutated TSA is significantly associated with a proximal colonic tumor location and more widespread CpG island methylation." (PMID 26883113, 2016).
colon carcinoma (continued). "Moreover, this test result matched with the general report that the frequency of BRAF mutation occurrence in Japanese colon cancer patients is ~4–5%." (PMID 25936694, 2015). "A colon cancer cell line with a BRAF V600E mutation was shown to escape vemurafenib inhibition by activating the epithelial growth factor receptor (EGFR); however, treatment of these cells with vemurafenib and an EGFR inhibitor prevented vemurafenib resistance and induced apoptosis." (PMID 25706985, 2015). "Notably, feedback gene expression upregulation has been reported with other inhibitors such as a BRAF inhibitor which causes upregulation of EGFR gene expression in colon cancer 26, in this case leading to therapeutic resistance." (PMID 26275572, 2015). "BRAF V600E mutation has been found in ~4.7% of the colon cancer patients in Japan." (PMID 25936694, 2015). "Finally, we found little evidence of association between CIMP and mutations, except for the well-known BRAF mutation in colon cancer and also little association with patient survival." (PMID 26463173, 2015). "BRAF mutation occurred in up to 80 % of skin cancers and 5-10 % of colon cancers." (PMID 26168967, 2015). "In contrast to colon cancer, rectal cancer missed V600E BRAF mutations." (PMID 26104511, 2015). "We have established a state-of-theart measurement system using QProbe (QP) method that allows simultaneous measurement of KRAS codon 12/13, p.G13D and BRAF mutation, and compared this method against Direct Sequencing (DS) using 182 specimens from colon cancer patients." (PMID 25936694, 2015). "We further analyzed the impact of BRAF mutation in the 126 colon-cancer patients." (PMID 25367198, 2014). "Our finding that FOXF1 was downregulated in the BRAF mutated cohort suggests that this gene might also play a role in oncogene-induced senescence in colon cancer." (PMID 23324568, 2013). "Downregulation of FOXD3 levels by promoter methylation in colon cancer might provide a favorable setting for either acquisition of a BRAF mutation or proliferation by RAS-RAF-MEK over-activation, similar to IGFBP7." (PMID 23324568, 2013). "Therefore, in pre-clinical studies, vemurafenib is strongly synergistic with EFGR inhibitors like cetuximab for colon cancers expressing BRAF V600E mutations." (PMID 23717811, 2013). "Finally, research into the sequence of such events is required to provide a better insight in the association between activating BRAF mutations and DNA methylation in colon cancer." (PMID 23324568, 2013). "However, they reported a higher HR of 2.82 (1.5–5.5) for BRAF mutation as a risk factor for right side colon cancer in the same report." (PMID 23056577, 2012). "CpG island methylation phenotype (CIMP), microsatellite instability, and BRAF mutation may have clinical significance in colon cancer." (PMID 22792460, 2012). "For example, methylation of T lymphocyte genes in lupus, the tumor suppressor gene Par-4 in transformed epithelial cells and p16(INK4A), p21(WAF1) and hMLH1 genes in colon cancer cells was found to be closely linked to the MAP kinase pathway with BRAF mutation." (PMID 23152800, 2012). "A number of studies also reported more prevalent BRAF mutations in right side colon cancer." (PMID 23056577, 2012). "Similarly, BRAF mutational status was available for 386 accessible incident colon cancer cases documented during 1,861,927 person years, of which 86 (22%) were BRAF mutated." (PMID 21738611, 2011). "Another consideration relates to the fact that the value of MSI tumor status as a prognostic or predictive marker in the adjuvant setting may be affected by mutations to other genes involved in colon cancer etiology, such the BRAF gene." (PMID 24212832, 2011). "As both BRAF and KRAS mutations have been observed in the earliest identified colonic neoplasms, and recent papers have provided evidence that induction of the ras oncogenic pathway will result in DNA hypermethylation, a causative effect of BRAF/KRAS mutations is likely." (PMID 20444249, 2010).